TCF7L2 (transcription factor 7 like 2)
Diseases named in the same sentence as TCF7L2 in open-access papers (continued):
Sharing a sentence is not in itself a finding about the gene and the disease.
type 2 diabetes (continued). "In the GLACIER cohort, eleven loci (including the known type 2 diabetes genes TCF7L2 and SLC30A8) were nominally associated with IFG cross-sectionally, and MTNR1B and G6PC2 were also associated with development of IFG in longitudinal analyses." (PMID 22984506, 2012). "The TCF7L2 transcription factor has been linked to a variety of human diseases such as type 2 diabetes and cancer." (PMID 22951069, 2012). "The interest in Tcf7l2 (also known as Tcf4) is recently heightened as it is thought to be significantly linked to type II diabetes, which is characterized, by insulin resistance and changes in glucose metabolism, especially in muscle." (PMID 23251550, 2012). "To conclude, our study suggests that the TCF7L2 risk variant modifies the protective association of dietary fibre intake with type 2 diabetes incidence and HbA1c levels." (PMID 22782288, 2012). "Comparing the reported genes to the MeSHOP profiles, TCF7L2 (Entrez Gene ID 6934) already had eight articles linking it to type 2 diabetes and hence a significant association was detected (corrected P = 0.018/raw P = 1.3e-7)." (PMID 23021552, 2012). "Since in several earlier studies fibre intake has been associated with protection against type 2 diabetes, we next analysed the effect of fibre intake on the risk of type 2 diabetes among different TCF7L2 genotype carriers." (PMID 22782288, 2012). "Previous genome-wide association studies revealed that TCF7L2 is a strong candidate for a type 2 diabetes gene." (PMID 23028378, 2012). "The TCF7L2 transcription factor is linked to a variety of human diseases, including type 2 diabetes and cancer." (PMID 22951069, 2012). "The TCF7L2 rs7903146 T allele was associated with a 44% (95% CI 33, 56) increased risk of incident type 2 diabetes (p = 4.6 × 10−19) in the MDCS." (PMID 22782288, 2012). "A strong genetic association relationship between Tcf7l2 polymorphisms and type 2 diabetes mellitus was identified." (PMID 21362171, 2011). "Variants in the TCF7L2 have initially been shown to be associated with an increased risk for type 2 diabetes (T2D) in a genome-wide analysis of the isolate population of Iceland." (PMID 21349175, 2011). "Association between TCF7L2 variants and significant coronary artery disease with respect to the presence of type 2 diabetes mellitus." (PMID 21423583, 2011). "TCF7L2 variants have been associated with type 2 diabetes, body mass index (BMI), and deficits in proinsulin processing and insulin secretion." (PMID 21814547, 2011). "In summary, we have identified significant associations between variants in CDKN2A/B, CDKAL1 and TCF7L2 and type 2 diabetes in a Han Chinese population." (PMID 20161779, 2010). "It is interesting to note that TCF4, a transcription factor, coded by TCF7L2, the most strongly associated and replicated type 2 diabetes susceptibility loci, is an integral part of Wnt-1 signaling." (PMID 20625434, 2010). "The transcription factor 7-like 2 gene (TCF7L2) rs7903146 T allele is constantly associated with Type 2 diabetes in various populations and ethnic groups." (PMID 21637413, 2010). "Genetic variants of this gene are associated with increased risk of type 2 diabetes, and extensive genome-wide association studies have identified TCF7L2 as a type 2 diabetes susceptibility gene." (PMID 21286314, 2010). "Noticeably, TCF7L2 SNPs have been demonstrated to have by far the biggest effect on the risk of developing type 2 diabetes, in comparison with all SNPs studied to date." (PMID 21286314, 2010). "The TCF7L2 polymorphism rs7903146 is the strongest single genetic variant associated with type 2 diabetes and has been convincingly replicated in multiple populations." (PMID 20161779, 2010). "In particular, SNPs located in TCF7L2 intron 4 and 5 – i.e. rs12255372 and rs7903146 – have shown robust associations with type 2 diabetes in a Danish and US cohort." (PMID 21286314, 2010).
type 2 diabetes (continued). "In our previous work, we confirmed that the T allele at single nucleotide polymorphism (SNP) rs7903146 located in intron 3 of TCF7L2 confers risk for incident type 2 diabetes in middle-aged African Americans and Caucasians." (PMID 20478041, 2010). "We have identified significant association between variants in CDKN2A/B, CDKAL1 and TCF7L2, and type 2 diabetes in a Han Chinese cohort, indicating these genes as strong candidates conferring susceptibility to type 2 diabetes across different ethnicities." (PMID 20161779, 2010). "Transcription factor 7-like 2 (TCF7L2) has been shown to be associated with type 2 diabetes mellitus (T2MD) in multiple ethnic groups in the past two years, but, contradictory results were reported for Chinese and Pima Indian populations." (PMID 19228405, 2009). "This was validated by qRTPCR analysis for the gene TCF7L2, in which SNPs so far have shown the strongest link to increased risk of type 2 diabetes." (PMID 19668377, 2009). "TCF7L2 is a transcription factor involved in Wnt/β-catenin signaling which has a variant known to be associated with risk of Type 2 diabetes and, in some studies, with risk of certain cancers, including familial breast cancer." (PMID 19732438, 2009). "Although association between rs12255372 and risk of Type 2 diabetes is thought to be due to impairment of insulin secretion, TCF7L2 has also long been known to have a role in Wnt/β-catenin signaling." (PMID 19732438, 2009). "TCF7L2 polymorphisms have been consistently associated with type 2 diabetes mellitus in different populations and type 2 diabetes mellitus is a major risk factor for cardiovascular disease, especially coronary artery disease." (PMID 19924244, 2009). "Other single nucleotide polymorphisms (SNPs) of the TCF7L2 gene have been shown to be associated with type 2 diabetes, although less strongly." (PMID 19615048, 2009). "We recently reported that type 2 diabetes risk alleles in TCF7L2, CDKAL1, and SLC30A8 impair proinsulin-to-insulin conversion." (PMID 19088850, 2008). "Our results provide important confirmation that variants of the TCF7L2 gene are strongly associated with type 2 diabetes in populations of South Asian origin, with similar effect sizes to those seen in white Caucasian populations." (PMID 18291022, 2008). "In conclusion, our results add to the rapidly expanding body of evidence that implicates TCF7L2 as an important risk factor for type 2 diabetes in multiple ethnic groups." (PMID 18291022, 2008). "SNP rs7903146 of the TCF7L2 gene was significantly associated with type 2 diabetes in the MASS-II population (OR = 1.57 per T allele, p = 0.0032), confirming, in the Brazilian population, previous reports of the literature." (PMID 19055834, 2008). "Recent studies have implicated variants of the transcription factor 7-like 2 (TCF7L2) gene in genetic susceptibility to type 2 diabetes mellitus in several different populations." (PMID 18291022, 2008). "Our results support recent findings that TCF7L2 is an important genetic risk factor for the development of type 2 diabetes in multiple ethnic groups." (PMID 18291022, 2008). "More recently, researchers at Decode Genetics reported strong association between variants in a novel susceptibility gene called TCF7L2 and type 2 diabetes in Icelandic diabetic patients." (PMID 18655717, 2008). "Analysis of the type-2 diabetes-associated SNPs CAPN10 g.4834T>C and TCF7L2 g.98386G>T, found their MAFs (23.1% and 24.8%, respectively) to be almost twice as common as type-2 diabetes in the Indian population (11.6%)." (PMID 18248681, 2008). "A recent paper has shown that a TCF7L2 haplotype (HapBT2D), characterised by the presence of the rs7903146 T allele, is associated with decreased BMI in subjects with type 2 diabetes." (PMID 18291022, 2008).
type 2 diabetes (continued). "The recent identification of common polymorphisms within the transcription factor 7-like 2 (TCF7L2) gene as risk factors for type 2 diabetes, however, provides fresh hope of unravelling the genetic basis of this complex disease." (PMID 18291022, 2008). "Of note was the Kashmiri group, which had significantly higher MAFs than the other groups for the CAPN10 g.4834T>C and TCF7L2 g.98386G>T SNPs associated with type-2 diabetes risk." (PMID 18248681, 2008). "Substantial association has been confirmed between variants in TCF7L2 and type 2 diabetes among broad ethnic backgrounds, including for example populations of UK, Dutch, Amish, Finnish, Swedish, French and US, Indian, and Japanese origin." (PMID 18655717, 2008). "The Wnt pathway effector gene TCF7L2 has been linked to type II diabetes, making it important to study the role of Wnt signaling in diabetes pathogenesis." (PMID 19165345, 2008). "TCF7L2 rs7903146 T allele is associated with a 1.57 increased risk for type 2 diabetes in a Brazilian cohort of patients with known coronary heart disease." (PMID 19055834, 2008). "Genetic polymorphisms of the TCF7L2 gene are strongly associated with large increments in type 2 diabetes risk in different populations worldwide." (PMID 19055834, 2008). "Two recent studies have reported that the TCF7L2 g.98386G>T variant is strongly associated with type-2 diabetes risk in a Asian Indians, and our frequency of this variant (24.8%) in this Indian cohort is close to that reported for control subjects (22%)." (PMID 18248681, 2008). "The rs7903146 and rs12255372 variants of TCF7L2 have been strongly associated with type 2 diabetes (T2D) risk in most populations studied to date." (PMID 18655717, 2008). "Recently, a new type 2 diabetes (T2D) susceptibility gene, transcription factor 7-like 2 (TCF7L2), was identified." (PMID 17683561, 2007). "A polymorphism in the transcription factor 7-like 2 (TCF7L2) gene has been found to be associated with type 2 diabetes in case-control studies." (PMID 17181866, 2006). "The TCF7L2 (rs7903146) polymorphism is the most powerful single genetic variant influencing type 2 diabetes risks identified to date." (PMID 17181866, 2006). "An association has recently been established between type 2 diabetes and variation in the transcription factor TCF7L2 gene in a large Icelandic study." (PMID 17181866, 2006). "Notably, Tcf7l2 has been strongly associated with type 2 diabetes and is involved in glucose homeostasis and insulin secretion in pancreatic β cells." (PMID 40971438, 2025). "TCF7L2 gene variants are one of the most potent genetic risk factors for type 2 diabetes, and new research indicates they may also affect how the body reacts to GLP-1 RAs." (PMID 40872522, 2025). "Furthermore, TCF7L2 has been implicated in numerous other diseases associated with type 2 diabetes, ranging from cardiovascular disease to cancer to liver disease." (PMID 40675550, 2025). "In the Algerian population, high dessert intake amplifies the association between the TCF7L2 rs7903146 T allele and type 2 diabetes: T-allele carriers with high dessert consumption exhibit a significantly higher risk of type 2 diabetes and elevated fasting plasma glucose levels." (PMID 41190158, 2025). "High dietary fiber intake may amplify the association between the TCF7L2 rs7903146 T allele and type 2 diabetes; among high-fiber consumers, the T allele is linked to elevated HbA1c levels, whereas this association is attenuated in low-fiber consumers." (PMID 41190158, 2025). "Similarly, TCF7L2 polymorphisms (rs12255372 and rs7903146) are among the strongest genetic risk factors for type 2 diabetes mellitus, influencing insulin secretion and glucose homeostasis." (PMID 40944253, 2025). "In addition to being the first gene found to be associated with type 2 diabetes, TCF7L2 remains the strongest and most significant association, replicated in multiple cohorts of different ancestries." (PMID 40675550, 2025).
type 2 diabetes (continued). "Genetic variants of TCF7L2 are strongly linked to development of type 2 diabetes." (PMID 39401200, 2024). "Moreover, investigations into common genetic variants linked to type 2 diabetes, such as TCF7L2, SLC30A8, and CDKAL1, underscore the interconnectedness of GDM and metabolic disorders." (PMID 38694942, 2024). "TCF7L2 has been associated with glucose metabolism in the past, especially in type 2 diabetes." (PMID 39060928, 2024). "Although the Wnt effector transcription factor 7-like 2 (TCF7L2) is closely associated with type 2 diabetes risk, the role of TCF7L2 in NAFLD development remains unclear." (PMID 36759348, 2023). "For the variants in both 95% credible sets from these colocalization analyses, the risk-increasing alleles for type 2 diabetes are associated with a lower BMI, a lower risk of knee osteoarthritis, and an increased expression of TCF7L2 in pancreatic islets and osteoarthritic cartilage." (PMID 37433298, 2023). "Indeed, one of the first discovered genetic associations with type 2 diabetes was with the Wnt pathway gene TCF7L2, potentially acting on adipose tissue to confer enhanced risk." (PMID 37337125, 2023). "TCF7L2 variants are the strongest genetic risk factor for type 2 diabetes." (PMID 36282337, 2023). "Additionally, it is known that common genetic variations of TCF7L2 are associated with type 2 diabetes mellitus and that subjects with its high-risk allele of TCF7L2 show impaired insulin secretion." (PMID 35453568, 2022). "A signif icantly lower occurrence of type 2 diabetes risk alleles TCF7L2 (103894T)and TCF7L2 (53341T) in the samples of indigenous Siberian peoples compared to Russians was observed, which agreeswith their lower susceptibility to metabolic disorders compared to the newcomer Caucasian population." (PMID 35434484, 2022). "For example, the transcription factor 7-like 2 (TCF7L2)-rs7903146 polymorphism is associated with increased risk of type 2 diabetes, and the response of insulin and insulin resistance to artichoke leaf extract (ALE) may be affected by this polymorphism." (PMID 35010984, 2021). "Polymorphism in TCF7L2 (TCF4) strongly correlates with an increased risk of type 2 diabetes." (PMID 33981287, 2021). "The possible involvement of TCF7L2 in type 2 diabetes pathophysiology became apparent following the identification in genome-wide association studies of SNPs in the TCF7L2 gene as amongst the most strongly associated with an increased risk of type 2 diabetes." (PMID 33068125, 2021). "In this way, we sought to explore the possibility that altered TCF7L2 expression in the adipocyte may contribute to type 2 diabetes risk by affecting crosstalk between multiple tissues involved in energy homeostasis." (PMID 33068125, 2021). "Might changes in TCF7L2 expression in adipose tissue contribute to the effects of type 2 diabetes-associated variants in humans?" (PMID 33068125, 2021). "Variation in the TCF7L2 gene has been associated with an increased risk of type 2 diabetes." (PMID 33594477, 2021). "TCF7L2 is the most known of those genes, which are associated with type 2 diabetes." (PMID 34674647, 2021). "Additionally, TCF7L2 was associated with type 2 diabetes in epigenetic studies performed in blood and pancreas." (PMID 31959221, 2020). "Several type 2 diabetes susceptibility genes are known to play a role in cancer development (e.g. TCF7L2, CDKN2A/B, AKT2, PPARG, PTEN and HNF1B) but the evidence is relatively scarce for shared genetic aetiology between type 2 diabetes predisposing alleles and the observationally associated cancers." (PMID 32705315, 2020). "Consequently, it will be interesting to assess if the expression levels of these human TCF7L2 exons are altered in type-2 diabetes patients carrying risk factor SNPs." (PMID 31829936, 2019).
type 2 diabetes (continued). "Given the role of peripheral serotonin in metabolic homeostasis and type 2 diabetes, this finding provides a first hint that the well-known impact of the TCF7L2 polymorphism on type 2 diabetes risk may involve a serotonin-dependent pathway." (PMID 31492908, 2019). "Genetic background analyses of type 2 diabetes in populations of different ethnic descent reproducibly identified single nucleotide polymorphisms (SNPs) of transcription factor 7-like 2 (TCF7L2) as one of the most important loci to predispose carriers for type 2 diabetes." (PMID 31492908, 2019). "However, the exact mechanisms through which TCF7L2 and respective polymorphisms alter metabolic processes and affect the susceptibility to type 2 diabetes remain to be established." (PMID 31492908, 2019). "TCF7L2 variants are one of the best biomarkers for the diagnosis of type 2 diabetes." (PMID 31695458, 2019). "Tcf7l2 is linked to type-2 diabetes outcome and the strongest risk factor SNPs are located in introns near human tcf7l2 exon 3a." (PMID 31829936, 2019). "Although the mechanisms through which TCF7L2 variation increases type 2 diabetes risk are largely unknown, recent evidence implicates altered incretin signalling." (PMID 31049640, 2019). "In a meta-analysis of type 2 diabetes from two African populations, we replicated the widely reported association at TCF7L2 (rs7903146) and identified a novel association signal at AGMO (rs73284431) that is distinct from previously reported signals in the region." (PMID 31049640, 2019). "Nevertheless, glucose-dependent suppression of AMPK activity, likely to mimic the effect of Lkb1 deletion on mTOR activity, may provide a means through which changes in glycemia modulate the direction of the effect of TCF7L2 variants on type 2 diabetes risk." (PMID 29967064, 2018). "TCF7L2 is located at one of the most strongly associated type 2 diabetes loci reported to date." (PMID 29392078, 2018). "In a recent study, we showed that the TCF7L2 rs7903146 (C/T) gene polymorphism may be associated to type 2 diabetes in Cameroonians." (PMID 28420445, 2017). "TCF7L2 was the only other gene associated with type 2 diabetes at nominal p <0.01 in our data." (PMID 28253288, 2017). "Interestingly, TCF7L2 single-nucleotide polymorphisms have shown the strongest association with type 2 diabetes in genome-wide association studies, and TCF7L2 has been proposed to regulate islet function." (PMID 27796421, 2017). "We could replicate our previous finding of interaction between TCF7L2 variants and fiber intake in relation to the risk of developing type 2 diabetes over time." (PMID 27551309, 2016). "TCF7L2 gene has been implicated for type 2 diabetes in many studies." (PMID 27168765, 2016). "The TCF7L2 rs7903146 shows the strongest association with type 2 diabetes, as compared to more than 65 other loci identified to date among Europeans, with each risk allele of rs7903146 associating with around 40 % elevated risk of type 2 diabetes." (PMID 27551309, 2016). "Our findings suggest then that TCF7L2 mutations or single-nucleotide polymorphism variants might modify both the degree of ischaemic myelin damage in patients with type 2 diabetes and their ability to remyelinate." (PMID 26955760, 2016). "Additionally, another TCF7L2 variant, rs12255372, showed a somewhat stronger interaction with fiber intake on type 2 diabetes incidence (Pinteraction = 0.005)." (PMID 27551309, 2016). "Genetic variations of the TCF7L2 gene are associated with the development of Type 2 diabetes (T2D)." (PMID 27230431, 2016). "In addition, the type 2 diabetes risk allele (T) in TCF7L2 rs7903146 and rs12255372 has been linked to impaired insulin secretion and incretin action, and more specifically, a reduction in the second phase of GLP-1-induced insulin secretion." (PMID 27623947, 2016). "TCF7L2 rs7903146 is the most common susceptibility variant for type 2 diabetes across the world." (PMID 26576435, 2015).